IL6 (interleukin 6)
Diseases named in the same sentence as IL6 in open-access papers (continued):
Sharing a sentence is not in itself a finding about the gene and the disease.
colon carcinoma (continued). "Altogether, findings obtained in our study concluded that M2 macrophage-derived exosomes transferred miR-155-5p into colon cancer cells to target ZC3H12B, which increased IL-6 expression and then promoted immune escape and tumor formation in colon cancer." (PMID 33718596, 2021). "The role of ADAM17 in colon cancer is thought to be linked to ADAM17-mediated shedding of EGF-R activating ligands, as well as IL-6 trans-signaling, which is also promoted by ADAM17 via the shedding of IL-6R." (PMID 33143292, 2020). "Recent studies have demonstrated that TLR4 expression and signaling induce an upregulation of IL-6 in different context such as colon cancer, Fragile X, and human bladder epithelial cells." (PMID 32230799, 2020). "RT-qPCR was carried out to investigate the expression of IL1β, IL6 and TNFα in colon cancer cells stimulated with LPS or siHMGB1." (PMID 32514250, 2020). "In our study, Trichomicin reduced the levels of IL-6 and TNFα in colon cancer tumor tissues, which indicated that it had potential as an adjuvant treatment for colon cancer." (PMID 32317968, 2020). "Based on these findings, we evaluated the antitumor effects of Trichomicin against colon cancer in a colorectal tumor animal model, and evaluated the role IL-6 and TNFα in these effects." (PMID 32317968, 2020). "These factors are suggested to be involved in colon cancer carcinogenesis, since the downregulation of IL-6 reduced the colon cancer development." (PMID 32380783, 2020). "CSF-2 and IL6 antibody blockade can inhibit the occurrence and metastasis of colon cancer in vivo, increase the proportion of M1 macrophages in tumor tissues, and reduce the proportion of M2 phenotypic TAMs in tumor tissues." (PMID 33224886, 2020). "In an inflammatory colon cancer model, stimulation by the IL-6/sIL-6R complex induced intra-tumoral growth of epithelial cells." (PMID 32209102, 2020). "In order to determine that JAK2/STAT3 signalling is indispensable for the tumour‐suppressive effect of FXR activation on colon cancer cells, colivelin and IL‐6, the agonists of JAK/STAT3 pathway, were adopted to treat FXR‐activated cells." (PMID 33164339, 2020). "As a typical immune cell, the regulatory T cell is demonstrated to modulate the secretion of TNF-α or IL-6/11/22 so as to affect colonic cancer progression." (PMID 32410986, 2020). "CAFs abundantly produce IL-6, particularly in the presence of colon cancer cells and the produced IL-6 enhanced VEGF production by CAFs, leading to angiogenesis." (PMID 33050237, 2020). "Conclusively, Trichomicin, a promising new drug candidate with antitumor activity, exerted antitumor effects against colon cancer through inhibition of the IL-6 and TNFα signaling pathways." (PMID 32317968, 2020). "On the contrary, down-regulated IL-6/GP130 improved 5-fluorouracil-based chemotherapy sensitivity in colon cancer." (PMID 30897064, 2019). "Previously, MSCs were shown to modulate tumorigenicity of colon cancer through interleukin-6 (IL-6) and promotes the formation of colorectal tumors in mice." (PMID 30764543, 2019). "Subsequently, IL-6 together with the ADAM17 shed soluble IL-6 receptor acts on intestinal epithelial cells via IL-6 trans-signaling to induce colon cancer formation, which can be blocked by the inhibitor of IL-6 trans-signaling, sgp130Fc." (PMID 31694340, 2019). "Blockade of IL-6 trans-signaling therefore offers a new therapeutic window downstream of the EGF-R for the treatment of colon cancer and possibly of other EGF-R related neoplastic diseases." (PMID 31694340, 2019). "Catalpol reduced inflammatory factors commonly found in colon cancer tumors such as IL-1β, IL-6, IL-8, COX-2, and iNOS." (PMID 31878316, 2019). "Studies have shown that elevated circulating levels of IL-6 mediated skeletal muscle cell death in severely cachectic mice with colon cancer." (PMID 31096595, 2019).
colon carcinoma (continued). "In colon cancer, IL-6 is known to be secreted by stromal fibroblasts, several types of immune cells, and by parenchymal cancer cells to activate STAT3 signaling, thereby mediating tumor-promoting effects." (PMID 30804456, 2019). "This stimulation leads to a secretion of IL-6 by MSCs which increase stemness properties of colon cancer cells." (PMID 31009502, 2019). "Following treatment of colon cancer tissue with high levels of the inflammatory mediator Interleukin-6 (IL-6), the formation of cell-in-cell structures increased compared with tissues exposed to low levels of IL-6." (PMID 31850347, 2019). "The CXCL family has long been reported as prognostic biomarkers in colon cancer, being involved with inflammatory processes, including genes such as IL-6, C5AR1, and C3 in the IL-6 module." (PMID 31469863, 2019). "Ellagic acid was shown to reduce the expression of NF-κB, COX-2, iNOS, TNF-α, and IL-6 in 1, 2-dimethylhydrazine-induced colon cancer." (PMID 30971953, 2019). "As observed in this study and supported by several previous reports, the stem-like CD44+/CD133+ colon cancer cells are chemo-resistant, a characteristic that is enhanced by IL-6 stimulation and the subsequent FRA1 deacetylation." (PMID 30804456, 2019). "IL-6 and IL-8 produced within the tumor microenvironment promote the growth and proliferation of colon cancer cells." (PMID 31878316, 2019). "We found that IL-6 induced EMT in colon cancer cells and that STAT3 phosphorylation was involved in this process." (PMID 30308035, 2018). "IL-6 can propagate colon cancer cell growth and unsurprisingly circulating levels of IL-6 are prognostic in colon cancer." (PMID 30081854, 2018). "4PBA in our study reduced the expression of IL-6 along with other inflammatory cytokines, which can be related to previous studies of attenuation of angiogenesis and tumor formation in colon cancer." (PMID 30326660, 2018). "In both CT26 and MC38 models of colon cancer, addition of bone marrow-derived macrophages to tumors led to increased IL-1β, IL-6, and TNF-α at significant levels with the exception of IL-1β in MC38 tumors." (PMID 30298062, 2018). "IL-6 enhanced the invasiveness of colon cancer cells, whereas metformin blocked their invasiveness, which agrees with the results of the migration assay." (PMID 30308035, 2018). "Upon treatment with IL-6, the 2 colon cancer cell lines showed decreased levels of E-cadherin and increased levels of phosphorylated STAT3, N-cadherin, SNAI1, and vimentin." (PMID 30308035, 2018). "Herein, we treated colon cancer cells with IL-6 to mimic the paracrine inflammatory microenvironment of tumor cells." (PMID 30363706, 2018). "We induced epithelial–mesenchymal transition in colon cancer cell lines via IL-6 treatment, which increased cell motility and promoted invasion." (PMID 30308035, 2018). "In western blot analysis, IL-6-induced phosphorylated STAT3 signals were faint in the metformin-treated colon cancer cell lines." (PMID 30308035, 2018). "In a colon cancer mouse model, IL-6 treatment stimulated key glycolytic genes, including PFKFB3 and aerobic glycolysis, whereas the anti-IL-6R antibody decreased glycolysis, suggesting an important role of IL-6 in cellular metabolism." (PMID 30603053, 2018). "Future studies are required to establish the impact of IL-6 attenuation on survival outcomes in colon cancer." (PMID 30081854, 2018). "To determine the effect of metformin on IL-6-induced motility changes in colon cancer cells, we performed a migration assay." (PMID 30308035, 2018). "Because tumorigenesis and progression are commonly driven by inflammatory microenvironment, we treated colon cancer cells with interleukin 6 (IL-6, a well-known inflammatory cytokine) to mimic the inflammatory microenvironment in vitro." (PMID 30363706, 2018). "This is the first in vitro study to demonstrate the EMT-suppressive function of metformin in IL-6-induced colon cancer." (PMID 30308035, 2018).
colon carcinoma (continued). "Colon cancer cell migration and invasion were activated by IL-6 and the expression of EMT markers was increased in cells treated with IL-6." (PMID 30308035, 2018). "This would explain why such mice expressed elevated levels of IL-6 that can promote malignant progression in colon cancer." (PMID 30119997, 2018). "The relationship between MUC2 and IL-6 gene expression and colon cancer patient prognosis was examined using the PrognoScan database." (PMID 28725043, 2017). "To further investigate the interaction between MUC2 and IL-6 in colon cancer, we compared the expression of MUC2 and IL-6 in normal colon and colon cancer tissues using the Oncomine database." (PMID 28725043, 2017). "Blocking IL-6 with IL-6 antibody treatment or IL-6 knockdown significantly inhibited the migration potential of RAB3C-overexpressing colon cancer cells." (PMID 28784136, 2017). "On the basis of the evidence presented above, we propose that RAB3C overexpression in colon cancer cells induces IL-6 exocytosis, thereby triggering JAK2 activation and STAT3 phosphorylation and inducing cancer cell metastasis." (PMID 28784136, 2017). "In colon cancer, IL-6 participates in almost every step of cancer progression, including tumor initiation, proliferation, migration, and angiogenesis, and IL-6 expression has been confirmed to be correlated with poor prognosis." (PMID 28784136, 2017). "Our results demonstrate that MUC2 downregulation and IL-6 overexpression correlate with human colon cancer metastasis." (PMID 28725043, 2017). "We thus measured the IL-6 production in the culture supernatant of each of the colon cancer cell lines." (PMID 28784136, 2017). "IL-6 increases the expression of DNMT1 in colon cancer cells and enhances nuclear translocation of DNMT1." (PMID 28103274, 2017). "Our previous study demonstrated that the suppression of MUC2 in CT26 colon cancer cells induces IL-6 secretion and plays an important role in tumorigenesis in an animal model." (PMID 28725043, 2017). "One of the major cytokines secreted by M2-TAM is IL-6, and IL-6’s oncogenic roles have been well established in different cancer types including colon cancer." (PMID 28241877, 2017). "We first confirmed that erythromycin suppresses the transcriptional activity of nuclear factor-κB and activator protein-1 and the expression of its downstream targets, interleukin-6 and cyclooxygenase-2 in human colon cancer cells." (PMID 28584401, 2017). "To do this we first compared IL-6 treated DLD1 derived STAT-3null A4 colon cancer cells versus STAT-3 reconstituted A4 cells." (PMID 28819304, 2017). "Patients with a lower level of MUC2 expression had a trend of higher IL-6 expression in colon cancer cells and specifically higher infiltration by immune cells (P = 0.0446)." (PMID 28725043, 2017). "The results of this analysis confirmed that the proximal MMP-1 promoter containing the GAS-like SBE was inducible by IL-6 in SW480 (1.2-fold) colon cancer cells, under conditions of low (1%) serum." (PMID 28819304, 2017). "Most importantly, inverse expression of the MUC2 and IL-6 proteins was observed in patients with stage II colon cancer." (PMID 28725043, 2017). "The objective of this study was to examine the signaling pathways mediated by the interaction between MUC2 and IL-6 during colon cancer metastasis." (PMID 28725043, 2017). "In this study, we present data from comparative biopsy analysis, confirming co-regulation of MMPs with inflammatory cytokines, such as IL-6, in colon cancer." (PMID 28819304, 2017). "We previously demonstrated that MUC2 suppression enhances IL-6 secretion in the colon cancer cell line CT2619." (PMID 28725043, 2017). "Another recent study looking at human colon cancer cell lines, confirmed the critical role for the IL-6/STAT3 pathway in enabling TNFR2 upregulation." (PMID 29163543, 2017).
colon carcinoma (continued). "We determined the MUC2 and IL-6 expression levels in 102 patients with stage IIA colon cancer and their correlation with clinicopathologic characteristics." (PMID 28725043, 2017). "In conclusion, this study is the first to examine the interaction between MUC2 and IL-6 protein expression in human colon cancer." (PMID 28725043, 2017). "In colon cancer, interleukin-6 (IL-6) is a tumor-promoting factor by inducing neoplastic cell proliferation through activation of the STAT3 oncogene in dysplastic epithelial cells, and its levels correlates with tumor size." (PMID 28448444, 2017). "We observed that the IL-6 production was positively correlated with the endogenous RAB3C protein level in a panel of colon cancer cell lines." (PMID 28784136, 2017). "To further confirm the role of the RAB3C-IL-6 axis in colon cancer metastasis, we analyzed the canonical pathway of IL-6 by examining previous data." (PMID 28784136, 2017). "Inflammatory cytokines such as IL-1α, IL-6 and TNFα are elevated in colon cancer and play important role in the mechanism of tumorigenesis." (PMID 26951793, 2016). "IL-6 promotes colon cancer cell proliferation, survival, migration, invasion, metastasis, angiogenesis and inflammation." (PMID 26896068, 2016). "A similar immunohistochemical IL6 expression pattern has been described in primary colon carcinoma and invasive mammary carcinoma." (PMID 26215971, 2015). "Tumor cells derived from epithelial tissues like mammary, prostate and colon carcinoma show increased IL6-induced expression of BCL-XL, Hsp70, cyclin A1, and Mcl1." (PMID 26215971, 2015). "Our results extend this observation and suggest an important role for p38α in the regulation of IL-6/STAT3 signaling in human colon tumors." (PMID 25890501, 2015). "In this study, we identified that ADSCs improved the malignant characteristics, including tumor growth and especially tumor initiation, of breast and colon cancer cells by secreting IL-6." (PMID 25797257, 2015). "In vivo experiments on wild-type mice have shown that IL-6 is significantly augmented at the colonic tumor environment, and the growth of colon tumors was suppressed when the mice were treated with antibodies against IL6R." (PMID 26321888, 2015). "Genetic downregulation of p38α in AOM/DSS-induced mouse colon tumors reduces tumor growth, which correlates with reduced levels of IL-6, IL-11, CXCL-1 and CXCL-2." (PMID 25890501, 2015). "Collectively, these results indicate that IL-6 as a key regulator that contributes to the ADSCs-induced enhancement of tumor-initiating properties and growth abilities in both breast and colon cancer cells." (PMID 25797257, 2015). "First, we examined the effects of IL-6 on tumor-initiating properties of breast and colon cancer cells." (PMID 25797257, 2015). "Here, we showed that ADSCs promoted not only tumor-initiating capacity but also tumor growth ability of breast and colon cancer cells through IL-6-related pathway." (PMID 25797257, 2015). "Together these results demonstrate that upon co-culture with cancer cells ADSCs can activate the JAK2/STAT3 pathways in both breast and colon cancer cells via induced IL-6 expression." (PMID 25797257, 2015). "But the ADSC-enhanced sphere generation of breast and colon cancer cells was significantly reduced by IL-6–neutralized antibodies." (PMID 25797257, 2015). "We demonstrated that stromal fibroblasts isolated from colon cancer produced significant amounts of IL-6, and stimulated cancer cells into enhancing the production of IL-6 as well." (PMID 26690480, 2015). "Increased levels of IL-6 in a murine colon carcinoma model correlated with the development of cachexia, whereas treatment with monoclonal antibody to murine IL-6 suppressed it." (PMID 24787299, 2014). "IL-6 has been shown to play a role in colon cancer in vivo, with high serum levels (>12 pg/mL) correlating with larger tumor size and liver metastasis." (PMID 25547486, 2014).
colon carcinoma (continued). "In the present study, we examined the effects of MUC2 on tumor cell growth, IL-6 secretion and the immune response in colon cancer." (PMID 25322805, 2014). "In conclusion, our results demonstrate for the first time that in colon cancer cells not only 1,25D3, but also the proinflammatory cytokines TNFα and IL-6 were able to induce the expression of CaSR." (PMID 24176760, 2014). "Further, IL-6 is elevated in the sera of patients with colon cancer and has been suggested to promote tumor cell growth and survival." (PMID 25478789, 2014). "In murine models of colon cancer, IL-6 increases the number and size of tumors, and IL-6 signaling through STAT3 promotes the growth and survival of tumor cells." (PMID 25478789, 2014). "Previously, IL-6 has been shown to activate STAT3 in colon cancer through phosphorylation on the tyrosine 705 residue." (PMID 24098947, 2013). "We demonstrate IL-6-mediated activation of STAT3 occurs in conjunction with the phosphorylation of RKIP in vitro in human colon cancer cells." (PMID 24098947, 2013). "As in the early phase of DSS induction, colonic tumor IL-6 (P<0.05) and possibly IL-11 (P = 0.07) mRNA expression was higher in Iron/DSS compared with Control/DSS mice but not TNF or IFNγ." (PMID 24223168, 2013). "For example, TNF-α and IL-1β are potent stimulators for MMP9 in astrocytes, and IL-6 induces overexpression of MMP9 in human colon carcinoma cells, and TNF-α and IL-1β also can induce activation of NF-κB." (PMID 22529521, 2012). "In clinical investigations, high IL-6 levels in the sera of patients with colon carcinoma correlate with tumor size." (PMID 22583829, 2012). "IL-6 is a proinflammatory factor that plays a critical role in the natural history of some malignancies, such as human plasma cell neoplasms, colon cancer, and HCC." (PMID 22641338, 2012). "For example, triggering a cancer cell line form mouse colon carcinoma (M26) with LPS leads to production of IL-6 and consequently inhibits T cells proliferation and NK cell activity." (PMID 23492674, 2011). "Down-regulation of S100A10 in human macrophages inhibits the plasmin-induced release of pro-inflammatory cytokines such as interleukin-6, which has been suggested to promote cell growth and apoptosis-escape of colon cancer." (PMID 22206547, 2011). "This concept has been observed in other disorders including the progression of colon cancer, where it has been proposed that classical IL-6 signaling predominates in acute stages of disease, while IL-6 trans signaling becomes important in chronic stages." (PMID 21799929, 2011). "In preliminary studies we found significantly higher levels of both pro–inflammatory cytokines (TNF–alpha, IL–6, IL–8) and anti–inflammatory cytokine IL–10 in colon cancer patients as compared to healthy subjects (unpublished observations)." (PMID 21254741, 2010). "IL-1β, IL-6, and IL-10 responses have been exhaustively investigated, particularly in their connection with tumor growth and metastatic spread in colon cancer resection." (PMID 19309495, 2009). "The purpose of the present study was to evaluate the regulation of IL-6 activity in human colon carcinoma cells by classical modulators in respect to possible consequences for tumour progression." (PMID 18205904, 2008). "Transduction of IL-6 signalling into up-regulation of c-myc expression results in enhanced growth of colon carcinoma cells." (PMID 18205904, 2008). "Although all cell types investigated had been shown to express ER-α and -β as well as the VDR, IL-6 expression in human colon carcinoma cells was only modestly, if at all, influenced by the steroid hormones 17β-E2 and 1,25-(OH)2D3." (PMID 18205904, 2008). "In human colon carcinoma cells derived from well and moderately differentiated tumours, IL-6 expression is low and only marginally affected, if at all, by PGE2, 1,25-dihydroxyvitamin D3, and 17β-estradiol." (PMID 18205904, 2008).